SSC4D (scavenger receptor cysteine rich family member with 4 domains)
Synonyms: SRCRB4D; SRCRB-S4D; S4D-SRCRB
Tractability: Antibody: UniProt places it where antibodies can reach, with high confidence; UniProt predicts a signal peptide or a membrane-spanning region; its Gene Ontology location is reachable by antibodies, with medium confidence.
Gene: Protein-coding gene on chromosome 7 (76,389,017 to 76,409,744, reverse strand). Ensembl gene ENSG00000146700.
Subcellular location: Secreted
Gene Ontology:
Molecular function: scavenger receptor activity
Biological process: vesicle-mediated transport
Cellular component: extracellular region; membrane
Genetic constraint (gnomAD): Loss-of-function variants: 55 observed, 50.87 expected, observed/expected ratio (o/e) 1.08, 90% interval 0.87 to 1.35. The upper end of that interval is the gene's LOEUF score, 1.35, which puts it in group 5 of 6, group 1 being the genes least tolerant of losing a copy. Missense variants: 771 observed, 697.05 expected, observed/expected ratio (o/e) 1.11, 90% interval 1.04 to 1.17. Synonymous variants: 338 observed, 294.67 expected, observed/expected ratio (o/e) 1.15, 90% interval 1.05 to 1.25.
Homologues: Orthologues: chimpanzee SSC4D (99% identical), macaque SSC4D (97% identical), dog SSC4D (90% identical), pig SSC4D (90% identical), guinea pig SSC4D (88% identical), mouse Ssc4d (88% identical), rat Ssc4d (86% identical), rabbit SSC4D (83% identical), tropical clawed frog ssc4d (56% identical). Paralogues in human: DMBT1 (44% identical), CD163 (35% identical), SSC5D (32% identical), CD163L1 (31% identical), SCART1 (31% identical), PRSS12 (27% identical), CD6 (26% identical), CD5L (24% identical), LGALS3BP (21% identical), LOXL2 (18% identical), LOXL3 (18% identical), LOXL4 (18% identical), and 3 more.
Diseases named in the same sentence as SSC4D in open-access papers:
SSC4D is named in the same sentence as 4 diseases in open-access papers, as found by Europe PMC text mining. Sharing a sentence is not in itself a finding about the gene and the disease.
SSC4D shares sentences with these, for which no sentence is quoted: asthma (1 paper); cancer (1); diabetes (1); liver steatosis (1).